FASN (fatty acid synthase)
Diseases named in the same sentence as FASN in open-access papers (continued):
Sharing a sentence is not in itself a finding about the gene and the disease.
cancer (continued). "Fatty acid synthase (FASN) upregulation is another mechanism that induces fatty acid accumulation in cancer cells." (PMID 36115986, 2022). "The FASN inhibitor TVB2640 has shown significant anti-tumor activity in cancer cell lines and xenograft models, but its clinical translation and application are limited due to its drug properties." (PMID 35743814, 2022). "Many cancer cells depended on FASN for proliferation and survival, which, in turn, are dependent on the synthesis of biological membranes." (PMID 36544904, 2022). "It is a long-standing observation that FASN is overexpressed in several cancer types and that KM upregulates its expression." (PMID 35882862, 2022). "Previous studies have shown that cancer cells reprogram lipogenic metabolism in response to the massive demand for macromolecules and bioenergy, and that increased expression of FASN is a prominent feature." (PMID 35898882, 2022). "Fatty acid synthase (FASN) is identified as one of the key lipogenic enzymes regulating de novo FA synthesis in cancer cells." (PMID 35721518, 2022). "Although we analyzed the role of FASN in pan-cancer from multiple perspectives, this study had some limitations." (PMID 36555243, 2022). "The increased FA availability allows FASN-produced FAs to be used by the cancer cells instead of being sequestered through Mb/ER binding." (PMID 35448537, 2022). "As a critical enzyme catalyzing the synthesis of fatty acids, FASN is overexpressed in multiple cancers and required for cancer stem cell (CSC) maintenance, tumor initiation and progression." (PMID 36333288, 2022). "According to reports, the expression levels of FASN in cancer cells is considerably higher than that in normal cells." (PMID 35566090, 2022). "FASN plays a key role in the occurrence and spread of numerous types of malignant tumors and is an attractive target for cancer treatment." (PMID 35566090, 2022). "Recently, there has been increasing interest in the finding that apoptosis resistance induced by FASN contributes to chemoresistance development in cancers." (PMID 36359776, 2022). "MIF secreted by cancer cells supports pulmonary carcinogenesis through the upregulation of fatty acid synthase (FASN) in specific murine TAMs." (PMID 35242705, 2022). "In cancer progression, it is known that FASN is a central enzyme that catalyzes a committed step in fatty acid synthesis." (PMID 35887068, 2022). "Higher activity of FASN supports tumor cell survival and overexpression was reported in different types of cancers." (PMID 36497226, 2022). "Although FASN is often highly expressed in these cancers, the FASN expression profile exhibits subtype-specific heterogeneity." (PMID 35448537, 2022). "Inhibition of fatty acid synthase (FASN) is a potential mechanism related to metformin treatment of drug-resistant cancer cells, which results in the downregulation of lipids and fatty acids." (PMID 35912231, 2022). "In the TME, CAFs often feature elevated lipid biosynthesis and upregulation of FASN expression, which promotes lipid transfer from CAFs to cancer cells and stimulates tumor growth." (PMID 36582801, 2022). "Pre-clinical studies show significant anti-cancer effects when lipid synthesis is inhibited by genetic and pharmacological inhibition of FASN." (PMID 35742953, 2022). "Several theories of the biology determining the poor prognosis of cancer patients with high BMI were postulated including increased serum insulin-like growth factor-1 and involvement of fatty acid synthase (FASN) pathways." (PMID 34342680, 2022). "Inhibiting the expression of these pathways decreases the expression of FASN, which in turn inhibits cell proliferation and promotes apoptosis, in both in vitro and in vivo cancer models." (PMID 35243817, 2022). "Fatty acid synthase is a rate-limiting enzyme for de novo lipid synthesis and is consistently found to be increased in multiple types of cancer, where it is thought to regulate stemness." (PMID 36233047, 2022).
cancer (continued). "FASN has been studied in various cancers, these studies report FASN overexpression correlates with tumor progression." (PMID 35163079, 2022). "The function of FASN in cancer has been intensively studied, and targeting FASN represents a promising therapeutic strategy for multiple cancers." (PMID 36333288, 2022). "We firstly assessed FASN expression and its clinical value in the context of cancer and showed that FASN was at a higher level in tumor tissues than that in the control tissues." (PMID 36555243, 2022). "FASN was found highly expressed in multiple cancers and closely related to poor prognosis, and notably, many studies have revealed that the downregulation of FASN can repress tumor progression via diverse mechanisms." (PMID 36172157, 2022). "The positive expression of FASN was significantly correlated with cancer recurrence and metastasis (X2 = 5.505, p = 0.025)." (PMID 34123778, 2021). "Surprisingly, USP14 rather reduced the protein levels and activity of FASN in cancer cells, although it slightly inhibited the ubiquitination of FASN." (PMID 34948233, 2021). "De novo free fatty acid synthesis requires the downstream target FASN, which is highly expressed in various cancers." (PMID 34959709, 2021). "The reduced c-Myc level and its reduced transcriptional activity reduce the expressions of acetyl-CoA carboxylase, fatty acid synthase, carnitine–palmitoyltransferase-1, and medium-chain acyl-CoA dehydrogenase in the cancer cells." (PMID 34741022, 2021). "Further, highly expressed fatty acid synthase (FASN) contributed to cancer malignancy and poor prognosis." (PMID 34620841, 2021). "While FASN inhibitors are known to be highly effective cancer drugs in cell culture, they are often only moderately effective in vivo." (PMID 33928023, 2021). "Tumor acidosis in hyperglycolytic cancer cells enhances the fatty acid synthesis through activation of FASN." (PMID 34692517, 2021). "Accordingly, the genetic deletion or pharmacologic inhibition of FASN prevents tumor development and invasive growth, indicating that FASN is a potential target for cancer therapy." (PMID 33401771, 2021). "FASN is a key enzyme in the de novo synthesis of fatty acids, which plays a crucial role in the proliferation and survival of cancer cells, as it provides cells with fatty acids for energy generation and ensures their proper membrane architecture." (PMID 33430277, 2021). "FASN is frequently upregulated in a multitude of cancers and is strongly correlated with a poor prognosis in many instances, as well as associated with chemoresistance and metastasis." (PMID 35006438, 2021). "Nowadays, FASN is an attractive therapeutic target because most cancer cells depend upon FASN-mediated de novo FAS, whereas the majority of normal cells prefer exogenous FAs." (PMID 35006438, 2021). "High glucose-driven resistance in cancer cells was associated with elevated expression of metabolic enzymes HKII, PFK1, GAPDH, PKM2, LDH-A, IDH3A, and FASN." (PMID 34692517, 2021). "Overexpression of fatty acid biosynthetic genes such as those encoding for fatty acid synthase (FASN), ATP-citrate lyase (ACLY), and acetyl-CoA carboxylase (ACC), have been reported in tumors of various cancer types." (PMID 34770949, 2021). "miR-320 inhibited the fatty acid synthase directly, which in turn reduced the de novo biogenesis of fatty acids in cancer cells and finally suppressed cancer cell proliferation, migration, and invasion." (PMID 33613101, 2021). "FASN plays a crucial role in lipid metabolism and has become an attractive target in clinical cancer treatment." (PMID 34539243, 2021). "Researchers showed that inhibiting or silencing SREBP-1 or FASN impeded cancer cell viability promoted by leptin." (PMID 34888248, 2021). "This is significant as FASN is known to upregulate LN metastasis through the differential regulation of VEGF-C/D expression in cancer cells and LECs." (PMID 34831316, 2021).
cancer (continued). "As reported by Richard Flavin, Giorgia Zadra, and Massimo Loda, natural sense and pharmacological inhibition experiments have shown the importance of FASN on proliferation and survival in multiple cancer cell lines." (PMID 34822423, 2021). "Since USP14 reduced FASN protein levels in cancer cells, it was necessary to confirm the deubiquitination of FASN by USP14." (PMID 34948233, 2021). "Namely, the expression levels of MAOB and LRP1 were downregulated in cancer tissues compared with paracarcinoma tissues, and the expression of FASN was upregulated." (PMID 34819038, 2021). "In the present study, we found that 142 out of 218 TNBC patients (65.1%) were positive for FASN in cancer tissue which was significantly higher than that in adjacent tissues." (PMID 34123778, 2021). "In most normal non‐adipose tissues, the abundance and activity of FASN are largely inhibited by adequate dietary fat, but in many human cancers, FASN abundance and activity are abnormally increased and are associated with poor prognosis." (PMID 33626208, 2021). "It is well known that FASN is a metabolic oncogene, and overexpression of FASN is commonly observed in cancer cells." (PMID 34948233, 2021). "FA metabolic reprogramming contributes to cancer adaption to antiangiogenic treatments, and the use of FASN inhibitors can inhibit tumor regrowth and metastasis after sunitinib treatment withdrawal." (PMID 34766135, 2021). "Further studies should be conducted to find direct targets of USP14 that can control FASN levels in cancer cells." (PMID 34948233, 2021). "Since the survival of tumor cells mainly depended on FASN-mediated de novo synthesis of fatty acids, FASN was considered as the one of the important targets for human cancer therapy." (PMID 35223868, 2021). "Consistent with the TCGA and GEO results, we also found that the expression levels of MAOB and LRP1 were downregulated in cancer tissues compared with paracarcinoma tissues, and the expression of FASN was upregulated." (PMID 34819038, 2021). "On the other hand, tumor cells require more lipid sources for cancer growth and survival, which is highly dependent on de novo lipogenesis through FASN." (PMID 34948233, 2021). "The positive rate for MET and FASN in cancer tissues of TNBC were higher significantly than those in the adjacent tissue." (PMID 34123778, 2021). "We show here, that the lipogenic enzyme FASN enables HER2 signaling to circumvent the anti-cancer activity of ER-targeting SERMs such as tamoxifen." (PMID 33800852, 2021). "Lipogenic enzymes like FASN and ACC1 are commonly overexpressed in cancer and associated with worse outcomes." (PMID 33968771, 2021). "Through a metabolomic analysis, we found that inhibition of FASN demonstrated very different metabolic profiles from inhibition of USP14, indicating that these enzymes have little association with cancer cell metabolism." (PMID 34948233, 2021). "We propose that heightened mitochondrial priming is the basis for the apoptotic hypersensitivity of cancer cells starved of FASN-synthesized de novo FAs." (PMID 34675185, 2021). "The precise signalling pathway regulating FASN expression in different cancers is yet to be established." (PMID 33939282, 2021). "Disruption of de novo FA synthesis therefore represents a promising pharmacological approach to cancer control, and numerous attempts have been made to block the enzymes that regulate FA synthesis, including FASN – the key enzyme in the process." (PMID 33928023, 2021). "In cancer cells, Sp1 promotes fat production by up‐regulating the expression of sterol regulatory element binding protein‐1c (srebp‐1c) and FASN." (PMID 33369233, 2021). "FASN is essential for initiating long-chain fatty acid synthesis, which is necessary to meet the ever-increasing demands of cancer cells for membrane, energy, and protein production." (PMID 34250022, 2021).
cancer (continued). "FASN uses substrates produced by the consequent activities of ACACA and ACLY enzymes, which, together with FASN have also been found to be deregulated in a number of cancer types." (PMID 34206240, 2021). "Cancer cells exposed to FASN blockers can, however, activate regulatory bypass loops that compensate for the ceased endogenous lipid supply." (PMID 33928023, 2021). "Although several inhibitors of FASN have been developed, there are many limitations to using FASN inhibitors alone as cancer therapeutics." (PMID 34948233, 2021). "Fatty acid synthase (FASN) plays an important role in cancer development, providing excess lipid sources for cancer growth by participating in de novo lipogenesis." (PMID 34948233, 2021). "We here add FASN-dependent endogenous lipogenesis to the list of metabolic pathways closely intertwined with apoptotic cell death in cancer cells." (PMID 34675185, 2021). "Cancer cells can satisfy their demand for FAs by active uptake from the bloodstream, and the requirement of FASN in malignant transformation would be unrelated to its capacity to cell-autonomously generate endogenous lipids." (PMID 34675185, 2021). "We therefore attempted to effectively inhibit cancer cell growth by using a FASN inhibitor in combination with an inhibitor of a deubiquitinating enzyme USP14, which is known to maintain FASN protein levels in hepatocytes." (PMID 34948233, 2021). "FASN catalyzes de novo lipogenesis and is commonly upregulated across many different cancers (17, –, 19)." (PMID 33208446, 2021). "FASN, the most studied lipogenic enzyme in cancer, is responsible for the production of palmitate (C16:0) from acetyl-CoA and malonyl-CoA substrates in the presence of NADPH." (PMID 35006438, 2021). "The overexpression of lipogenic enzymes, such as fatty acid synthase (FASN) in several cancers has been correlated with cancer progression, poor prognosis and resistance to chemotherapy." (PMID 34359950, 2021). "Orlistat is a classical inhibitor of FASN and has exhibited its anti-cancer effects in the past decade." (PMID 34507580, 2021). "A major roadblock to the clinical application of FASNis is that the mechanism behind the resistance versus sensitivity of cancer cells to death signaling triggered by FASN blockade remained poorly understood." (PMID 34675185, 2021). "Nonetheless, higher levels of FASN have been detected in various types of cancer and demonstrated a correlation with malignant degree, which implies probable dysregulation of FASN in some pathological conditions." (PMID 34642298, 2021). "Fatty acid synthase (FASN), the key enzyme of DNL process, is overexpressed and hyperactivated in cancers with a high risk of disease recurrence and death." (PMID 34205356, 2021). "Many studies have shown that inhibition of FASN activity by pharmacological drugs and siRNAs induces apoptosis of cancer cells in vitro." (PMID 34948233, 2021). "The demonstration of target engagement and early signs of clinical activity in cancer patients receiving next-generation FASNis—TVB-2640 —has reignited interest in FASN as a target for new drug development." (PMID 34675185, 2021). "This can be interpreted as meaning that inhibition of USP14 does not help in terms of modulating the metabolic pathways in the cancer cells by FASN." (PMID 34948233, 2021). "FASN is primarily expressed in normal cells at a low level and highly expressed in cancer cells and preneoplastic lesions, including PCa, with high lipid metabolism." (PMID 34977875, 2021). "Inhibitors of the lipogenic enzyme fatty acid synthase (FASN) have attracted much attention in the last decade as potential targeted cancer therapies." (PMID 34675185, 2021). "As a key lipogenic enzyme catalyzing the terminal steps in the de novo biogenesis of fatty acids, fatty acid synthase (FASN) has been established to confer malignant tumor growth and survival." (PMID 34462429, 2021).
cancer (continued). "Beyond an alternative source of acetyl-CoA production, acetate is also implicated in initiating epigenetic regulation to lipogenic genes of FASN, for cancer cell survival under hypoxic stress." (PMID 34888248, 2021). "The consensus is that traditional, SREBP2/HMGCR signaling is the major modulator for cholesterol synthesis and SREBP1/FASN signaling governs fatty acid synthesis in various cancers." (PMID 33665967, 2021). "The expression and activity of enzymes involved in lipid metabolism are significantly increased in many cancer cells, such as fatty acid synthase (FASN) and Acetyl-coenzyme A carboxylase (ACC)." (PMID 34539243, 2021). "FASN modulates cellular energetics and membrane architecture, thereby influencing oncogenic signaling and sustaining cancer cell growth and survival." (PMID 33759347, 2021). "Alleviation of FASN expression in high glucose condition by curcumin can be expected to chemosensitize cancer cells." (PMID 34692517, 2021). "Consistently, pretreatment with fatostatin or TVB‐3166, which are pharmacological inhibitors of SREBP‐1 and FASN, respectively, also impeded cancer cell growth promoted by leptin." (PMID 33226729, 2021). "Fatty acid synthase (FASN) is the only human lipogenic enzyme available for de novo fatty acid synthesis and is often highly expressed in cancer cells." (PMID 33742137, 2021). "Upon hypoxic stress, different cancer cells had different cell-type-specific regulation of FASN, increased, decreased or unaffected." (PMID 34823530, 2021). "USP2a protects FASN from proteasomal degradation, inhibiting apoptosis and increasing cancer cell proliferation." (PMID 34948233, 2021). "FASN catalyzes the biosynthesis of palmitate which is essential for lipid synthesis and the generation of membrane structures in rapidly dividing cancer cells." (PMID 32178271, 2020). "Among the enzyme that regulates lipid metabolism, FASN is an important one and it correlates with poor prognosis in various types of cancer and also interferes with drug efficacy." (PMID 32211323, 2020). "The upregulation of FASN in CAFs provides the central precursor of lipid synthesis-fatty acid for cancer cells to promote the synthesis of downstream lipids, such as phospholipids and sphingolipids." (PMID 32327627, 2020). "For example, FASN up-regulation and increased activity represent one of the most frequent phenotypic alterations in cancer cells." (PMID 33027921, 2020). "Fatty acid synthase (FASN), the crucial enzyme for the de novo lipogenesis, also plays an important role in maintaining cancer stemness." (PMID 32641978, 2020). "Several studies demonstrated that impairment of SREBP-1/FASN/lipogenesis and the AR axis leads to apoptosis in cancer cells." (PMID 32276528, 2020). "Extensive studies have focused on the cytoplasmic FA synthesis system, which is a type I FA system or FASN, and have sparked huge interests to investigate the roles of FASN in cancer." (PMID 32872164, 2020). "For example, FASN, which synthesizes of palmitate from acetyl-CoA and malonyl-CoA, has been widely reported in various types of cancer." (PMID 32850862, 2020). "FASN plays an important role in palmitate synthesis which is a precursor of fatty acids, and is upregulated frequently in many human cancers." (PMID 32714863, 2020). "Consistently, our results demonstrated that SIK2 promoted fatty acid synthesis of OC cells through up-regulation of FASN, which further support FASN as a critical oncogene in cancer progression." (PMID 31932581, 2020). "Both COX-2 and FASN activities modulate cancer signaling and have been shown to modulate cell proliferation and survival." (PMID 32811515, 2020). "Fatty acid synthase, a key enzyme of de novo lipogenesis, is an attractive therapeutic target in cancer." (PMID 32850342, 2020). "FASN inhibitors reduce cancer cell viability and proliferation, thereby inducing cell death via apoptosis both in differentiated cells and GICs." (PMID 31936544, 2020).